IL6 (interleukin 6)
Diseases named in the same sentence as IL6 in open-access papers (continued):
Sharing a sentence is not in itself a finding about the gene and the disease.
melanoma (continued). "Oxidative stress induced by hypoxia in the melanoma as well as factors secreted by melanoma cells stimulate MAFs to secrete cytokines and growth factors such as VEGF, stromal derivative factor-1 (SDF-1 or CXCL12) and IL-6 thus promoting invasion into the melanoma." (PMID 32984031, 2020). "As both IL6 and PTHrP are expressed in some melanoma cell lines, this may be a conserved mechanism worthy of further investigation." (PMID 31323160, 2020). "Similarly, our work also indicated that Abx combined with the anti‐tumor drug DSF/Cu2+ had significantly inhibited the tumor growth in the melanoma‐bearing mice, accompanied by the reducing of inflammatory cytokines IL‐1β, IL‐6, and TNF‐α." (PMID 32750218, 2020). "Under the assumption that IL-6 can be excreted by melanoma cells and may stimulate autocrine growth, the parallel decrease of IL-6 in these patients might suggest that blockade of PD-1 did interrupt this putative autocrine loop." (PMID 32188047, 2020). "Moreover, progression of melanoma metastases secreting IL-6 should result in a parallel increase of both S100B and IL-6, thus imitating an immunologic response." (PMID 32188047, 2020). "Indeed, recent data from large cohorts of immunotherapy‐treated melanoma patients confirm elevated IL‐6 at baseline as a poor prognostic factor." (PMID 32383556, 2020). "CRPs are induced in the liver by IL‐6 which is upregulated by activation of NF‐kB by IL‐1β so this is again indirect evidence for an adverse effect of activated inflammasomes on immune responses against melanoma." (PMID 32027447, 2020). "Similarly, genes related to melanoma invasion were downregulated in SIRT2-deficient melanoma cell lines (e.g., HLA-DRA, IL-6, CD74, and HLA-DRB1 in the SSW30 clone, Dataset S1; PTPRZ1, FST, and NRCAM in the SSM15 clone, Dataset S2)." (PMID 31091806, 2019). "To determine if IL-6 and IL-8 are produced within melanoma tumors, we determined the cellular expression of IL-6 and IL-8 by performing immunohistochemistry (IHC) on paraffin-embedded melanoma tumors." (PMID 31781510, 2019). "Melanoma cells and tumor-derived fibroblasts could express high levels of IL-1β, IL-6, TGF-β, and IL-23, which provide an optimal proinflammatory cytokine milieu for Th17 cells expansion." (PMID 30800130, 2019). "They express high levels of IL-1β and IL-6, which may also contribute to Th17 cells expansion in melanoma." (PMID 30800130, 2019). "Importantly, we observed a previously unrecognised substantial increase in IL‐6 secretion from BRAFi‐R melanoma cells paralleling the elevated invasive migration of these cells." (PMID 30582770, 2019). "Due to the practical limitations of migration and invasion assays, we could not determine conclusively whether the combined antimigratory/invasive effect of IL‐6 Ab and Box5 treatment on BRAFi‐R melanoma cells was additive or synergistic." (PMID 30582770, 2019). "Additionally, we found that cell lines derived from the tumors of melanoma patients secrete both IL-6 and IL-8." (PMID 31781510, 2019). "Furthermore, in contrast to the parental BRAFi‐sensitive melanoma cells, IL‐6 and WNT5A signalling independently promote the invasive migration of BRAFi‐R melanoma cells." (PMID 30582770, 2019). "In concept, the increased expression of PLTP in the NM OMMs observed in the present study may be consistent with the production by the tumours of interleukin 6, which has been shown to inhibit melanoma growth." (PMID 31019223, 2019). "However, the IL‐6/WNT5A positive feedback loop present in parental melanoma cells is lost during development of acquired BRAFi resistance in melanoma cells." (PMID 30582770, 2019). "Lin Wang group reported that IL-17 enhanced melanoma growth due to its direct effects on IL-17 receptors expressing cells, such as melanoma cells, fibroblasts, endothelial cells, and DCs, via promoting their secretion of IL-6." (PMID 30800130, 2019).
melanoma (continued). "However, we identified that at least one such factor, IL‐6, increases melanoma cell expression of WNT5A through a p38‐MAPK signalling pathway." (PMID 30582770, 2019). "Furthermore, high plasma levels of IL-6 correlate with the frequency of MDSCs in the circulation, and the frequency of circulating MDSCs correlates with the overall survival of melanoma patients." (PMID 31781510, 2019). "Additionally, IL-6 signaling has been shown to increase metastasis in melanoma and other types of tumors." (PMID 31781510, 2019). "In summary, this data suggests that IL-6 and IL-8 produced within melanoma tumors, and the resulting expansion and recruitment of MDSCs, may strongly contribute to melanoma-induced immunosuppression." (PMID 31781510, 2019). "While we did not conclusively determine the sources of IL-6 and IL-8 in the plasma, we identified a correlation between the magnitude of melanoma tumor staining and the concentrations of IL-6 an IL-8 in plasma, suggesting that these cytokines are produced in part by the tumor." (PMID 31781510, 2019). "Besides the evaluation of CXCL1 levels in the melanoma microenvironment, we also analyzed the effect of the fatty acids treatment on in vitro and in vivo levels of IL-6, a pro-inflammatory cytokine, and IL-10, a classical anti-inflammatory cytokine." (PMID 31374840, 2019). "The primary objective of this study is to determine the role of IL-6 and IL-8 in the recruitment and immunosuppressive functions of MDSCs in melanoma patients, and how IL-6 and IL-8 may alter the clinical outcomes of melanoma patients." (PMID 31781510, 2019). "On the other hand, it has been reported that elevations in the pre-therapy serum concentrations of the cytokines IFN-γ (P < 0.0001), IL-6 (P < 0.0007), and IL-10 (P < 0.0001) are predictive of treatment efficacy in patients with advanced melanoma receiving nivolumab." (PMID 29623257, 2018). "The results of an experiment with mice revealed that the oncogenesis of melanoma and prostatic or gastric cancers could be inhibited by blocking of the IL-6/STAT3 signal pathway." (PMID 29693005, 2018). "Moreover, a phase 2 study revealed that pretreatment high level of IFN-γ, IL-6, and IL-10 in peripheral blood were relevant to increased objective response rate in melanoma patients receiving nivolumab." (PMID 30139382, 2018). "Noticeably, serum IL-6 level was found to be significantly high in advanced melanoma patients." (PMID 29219852, 2017). "For example, curcumin, when delivered as polyethylene glycol (PEG) conjugate along with Trp2 peptide vaccine, resulted in reduced IL-6 levels and down-regulation of immunosuppressive factors (regulatory T cells, myeloid-derived suppressor cells) in a melanoma-bearing mouse model." (PMID 28273819, 2017). "We then sought to determine whether IRE1α, the central mediator in the XBP1 splicing process, is involved in the regulation of IL-6 expression in melanoma." (PMID 28222747, 2017). "Because IL-6 is considered to be a critical player in promoting cell proliferation and progression and even a prognostic biomarker of melanoma, the RNase activity of IRE1α may be a promising therapeutic target." (PMID 28222747, 2017). "Our data demonstrated that AR42 reduced gp130 levels by ∼40% and those of IL-6RA by ∼80% which collectively argues that overall IL-6 paracrine/autocrine signaling may be reduced in AR42 treated melanoma tumors." (PMID 28146421, 2017). "IL-6 levels can be reduced by EGCG in breast cancer TME, as part of regulation of tumor-associated macrophages (TAMs), and IL-18 can be inhibited by resveratrol in melanoma TME, leading to reduced metastasis." (PMID 28273819, 2017). "However, in our previous study using this same line of CD4+ T lymphocyte-specific SHP2 knockout (SHP2CD4−/−) mice, we found that SHP2 deletion promoted progression and metastasis of melanoma via IL-6-myeloid derived suppressor cells cascade." (PMID 27935860, 2017).
melanoma (continued). "As IL-6, IL-8, and GROα have already been demonstrated to be important cytokines for melanoma growth and progression, this provides a link between IL-1 signaling in the stroma and melanoma growth support." (PMID 28450382, 2017). "In addition, siRNA silencing of WNT5A expression and the inhibition of endogenous WNT5A signalling using Box5 significantly reduced IL-6 secretion in WM852 melanoma cells." (PMID 27191257, 2016). "Furthermore, Atg5 knockdown in human melanoma cells enhanced IL-6 production and proliferation of anti-tumorigenic CD8+IFN-γ+ and CD4+IFN-γ+ T cells." (PMID 27124579, 2016). "Early studies implicated IL-6 and its major effector STAT3 as pro-tumorigenic agents in many cancers, including breast, lung, colon, prostate, ovarian, and hematological cancers as well as melanoma." (PMID 27107418, 2016). "IL-6, which is involved in melanoma survival, can activate STAT3 through JAK." (PMID 26784177, 2016). "Taking into account these findings, we set out to investigate whether WNT5A can regulate IL-6 expression and vice versa in a feedback loop in melanoma cells." (PMID 27191257, 2016). "Importantly, both IL-6 and osteopontin up-regulated chemokine mRNA levels in a time course dependent manner in the melanoma cells." (PMID 27049717, 2016). "Several IL6-associated cytokines have growth factor activity, and inflammatory mediators such as HMGB1, IL23, and IL17 can promote tumor growth by activating the IL6-STAT3 pathway in a mouse model of melanoma." (PMID 27163161, 2016). "IL-6 induces WNT-5A in melanoma cells via p38 which, in turn, mediates cell migration." (PMID 26514730, 2016). "We further delineate that expression of osteopontin, IL-6 and the melanoma derived chemokine C-X-C motif ligand 1 (CXCL1) in the bone marrow increases after high fat diet, predisposing melanoma cells to home into the bone likely due to enhanced osteoclast activation." (PMID 27049717, 2016). "To test our hypothesis that WNT5A and IL-6 could co-operate to accelerate melanoma metastasis, we first analysed whether their gene expression levels correlated with the invasive potential of melanoma cell lines." (PMID 27191257, 2016). "Thus, in melanoma patients, IL-6 increases with stage, as does TNF-alpha and IL-8; IL-6 being positively correlated with other serum markers tested in our patients, like S100 and MIA31,94." (PMID 32309563, 2015). "IL-6-mediated Th1 suppression may be involved in a recent finding that the level of IL-6 is correlated with clinical outcome in melanoma patients receiving immunotherapy." (PMID 25850032, 2015). "IL-6 itself plays an important role in melanoma progression." (PMID 26393652, 2015). "The ability of catecholamines to induce in melanoma cells the expression of the pro-inflammatory and pro-angiogenic interleukin-6 (IL-6), interleukin 8 (IL-8) and vascular endothelial growth factor (VEGF) prompted us to study the role of β-AR functions within tumor microenvironment." (PMID 25474135, 2015). "As we had hypothesized that phosphorylation at of STAT3 Y705 conferred anoikis resistance to melanoma cells, IL-6 treatment would enhance anoikis resistance in these cells." (PMID 25216522, 2014). "In the present research, it was approved in A549 cells that the NE-induced up-regulation in both protein and gene levels of VEGF, IL-8 and IL-6 was chiefly mediated by β-AR/cAMP/PKA signaling pathway which had been found to play a key role in mouse xenografts of melanoma and ovarian cancer." (PMID 24555849, 2014). "We demonstrate that DCOVA/IL-6 vaccine up-regulates expression of DC maturation markers, secretes transgene-encoded IL-6, and more efficiently stimulates OVA-specific CTL responses and therapeutic immunity against OVA-expressing B16 melanoma BL6-10OVAin vivo than the control DCOVA/Null vaccine." (PMID 24690994, 2014). "Moreover noradrenaline (NORA), at stress-related concentrations, has been shown to up-regulate VEGF, IL-, and IL-6 expression in different human melanoma cell lines." (PMID 23517603, 2013).
melanoma (continued). "Therefore, IL6 is able to mimic the effects of the SSMC to favor the melanoma-initiating cell phenotype." (PMID 24344100, 2013). "Many cancer cells, including e.g. prostate, breast, and colon cancer or melanoma, may produce large amounts of IL-6 and express the IL-6R/gp80 and gp130 receptor subunits, which allow them to respond to IL-6 stimulation even in an autocrine manner." (PMID 23517603, 2013). "Hence, STAT3 activation is required for the acquisition of the melanoma-initiating cell properties induced by the SSMC or by IL6." (PMID 24344100, 2013). "Thus we investigated if, in mice bearing B16-F10 melanoma metastases, increased circulating IL-6 did affect CRH production." (PMID 23517603, 2013). "In addition, NF-κB activation increased STAT3 activation through up-regulation of interleukin-6 (IL-6) in melanoma cells." (PMID 23402362, 2013). "Moreover, BRMS1 has been shown to negatively regulate melanoma angiogenesis by suppressing NF-κB activity and IL-6 expression." (PMID 22200669, 2012). "IL-6 is also produced by several epithelial cancer cell lines and it may act as possible growth factors in advanced melanoma." (PMID 17953739, 2007). "For example, in melanoma cells, IL-6/Stat3 function is modulated by the stage of tumor progression." (PMID 17925034, 2007). "Activated endothelial cells can indeed produce tumour cell growth factors, for example IL-6 in the vertical growth phase of melanoma, or matrix remodelling enzymes that facilitate tumour cell motility and invasion, as demonstrated in skin carcinogenesis models." (PMID 15743502, 2005). "As melanoma cells are known to produce Il-6, serum CRP might reflect Il-6 production from the tumour." (PMID 15280926, 2004). "Taking it all together we may suggest an interplay between HLA-G and IL-6 in melanoma progression." (PMID 41268555, 2025). "IL-6 blockade could improve ICIs induced antitumor efficacy in melanoma patients." (PMID 40519900, 2025). "A significant difference between IL-6 supernatant concentrations was observed between the control leukocyte and those stimulated with recombinant HLA-G at 100ng (p<0.001) and the control leukocyte and those stimulated with LEVs from melanoma patients in a proportion 1:10 (p=0.01)." (PMID 41268555, 2025). "Targeting IL-6 or its signaling pathways, such as by using IL-6 receptor antagonists, may provide new therapeutic strategies for improving clinical outcomes for patients with melanoma." (PMID 40699636, 2025). "However, Th2 prevalence could be further promoted by IL6, as indicated by an increased abundance of Th2 and a concomitant decrease of Th1 cells in advanced melanoma (bottom)." (PMID 39544930, 2024). "Additionally, targeting IL-6 or its signaling could open avenues for improving the immune responses to melanoma." (PMID 39336572, 2024). "Furthermore, based on our new findings, it suggests that RIPK4 may play a pivotal role in regulating the expression of IL-8 and IL-6 in response to TNF-α stimulation of melanoma cells." (PMID 38656555, 2024). "Several IL-6 inhibitors are currently in clinical trials for various malignancies, and our findings suggest that they may hold promise for patients with HCV-associated melanoma as well." (PMID 39336572, 2024). "Finally, the constitutive activation of NF-κB in melanoma cells also drives the augmented expression of endogenous chemokines, such as interleukin (IL)-1, IL-6, IL-8, and vascular VEGF, which, when transcriptionally stimulated, are assumed to increase melanoma progression." (PMID 39334716, 2024). "Since we observed that both melanoma-derived soluble factors as well as recombinant IL-6 activate the STAT3/SOCS3 pathway in microglia, we asked if IL-6 is present in the of the melanoma cells and whether microglia regulate the secretion of this cytokine from melanoma." (PMID 37296634, 2023).
melanoma (continued). "Furthermore, in combination with the hypoglycemic agent metformin, a drug largely used for type 2 diabetes, the EGCG inhibited the NF-kB/STAT3 signaling pathways, resulting in reduced melanoma growth and metastatic potential, and decreased pro-inflammatory mediators such as IL-6, IL-10 and TNF-α." (PMID 36768978, 2023). "Therefore, Mohapatra’s work demonstrated that the acquired resistance to BRAFi triggers a relevant increase in IL-6 secretion in BRAF V600E melanoma cells and that the inhibition of both proteins alters cell invasion capability representing a possible therapeutic target." (PMID 37627054, 2023). "Also depending on the results of this trial, targeting IL-6 might represent a clinically feasible treatment option, particularly for melanoma patients experiencing PLR." (PMID 35841421, 2023). "Interestingly, we found a correlation between increased levels of IL-6, IL-8, TNF-α and the accumulation of circulating PMN-MDSC in metastatic but not in non-metastatic patients, underlining their role in the melanoma progression." (PMID 36860876, 2023). "Thus, by dampening IL-6 production by melanoma cells, targeted therapy might counteract the pro-tumoral properties of ILC3s and skew them towards an anti-melanoma phenotype." (PMID 36765891, 2023). "In this same report, a retrospective analysis of 31 patients with melanoma further showed concurrent medication with IL-6–blocking agents (for other indications) could mitigate immune-related adverse events without compromising the antitumor activity of immune checkpoint blockade." (PMID 36881480, 2023). "Therefore, based on this background, it is plausible that glucocorticoids and catecholamines may influence melanoma growth and IL-6 production in its metastatic cells." (PMID 36766760, 2023). "Interestingly, preliminary results presented at the ESMO Congress 2021 from an ongoing Phase II clinical trial in 41 patients with unresectable melanoma treated with a combination of ipilimumab, nivolumab and anti-IL-6 antibodies reported an encouraging 60% response rate." (PMID 36007304, 2022). "Thus, OSM/IL-6 resistance of melanoma cells in the late-stage patients may benefit from histone deacetylase inhibitor Trichostatin A." (PMID 35495152, 2022). "Furthermore, increased IL-6 and IL-8 serum levels after anti-PD-1/PD-L1 treatment are associated with no response in non-small cell lung carcinoma and melanoma patients." (PMID 35359980, 2022). "Moreover, fibroblasts cultured in the presence of metastatic melanoma secretome exhibited a higher level of FAP-α (in both experimental models—CAFsINS, CAFsCM), and IL6 (only in the case of CAFsCM) in comparison to cells incubated with melanoma cells derived from primary tumors." (PMID 35538545, 2022). "Therefore, it is plausible that inhibition of IL6/ STAT3 pathway by elevated S100B in melanoma cells could be beneficial to early stage tumors as a way to prevent anti-proliferative effects of IL6 and to avoid immune-related destruction." (PMID 34411141, 2021). "Vitreous fluid of eyes with melanoma was shown previously to contain an elevated level of IL-6 (along with other cytokines/chemokines) compared to the healthy counterparts, suggesting that—via the prolonged activation of STAT3—it may contribute to the formation and maintenance of these tumors." (PMID 34884773, 2021). "Thus, the S100B-dependent inhibition of IL6 expression and secretion into a stress-free microenvironment could facilitate melanoma cells to escape the immune surveillance during melanoma progression." (PMID 34411141, 2021). "I-BET151 inhibits NF-kB activation in melanoma by targeting BRD2, causing cycle arrest, promoting apoptosis, and inhibiting the production of cytokines (e.g., IL6 and IL-8) and chemokines (e.g., CXCL10 and CCL5), which indicates that I-BET151 may have a therapeutic effect on melanoma." (PMID 34540687, 2021).